NRAS (NRAS proto-oncogene, GTPase)
Diseases named in the same sentence as NRAS in open-access papers (continued):
Sharing a sentence is not in itself a finding about the gene and the disease.
melanoma (continued). "Other subsets of melanoma benefit less from targeted therapies (uveal melanoma, acral melanoma, melanomas mutant in NRAS and triple-negative melanomas)." (PMID 35624662, 2022). "We also confirmed that the LATS1-SMAC endogenous interaction is regulated in a RASSF1A-dependent manner in another BRAF-driven melanoma cells SK-Mel239 and in the NRAS-driven melanoma cells SK-Mel2." (PMID 35941108, 2022). "Collectively, our results suggest that HSPB8 has an antitumoral action in melanoma cells characterized by BRAF and NRAS mutations." (PMID 36400750, 2022). "The present study compared RNA editing as well as gene expression in tumour cell lines from melanoma patients of short or long metastasis-free survival, patients relapsing or not after immuno- and targeted therapy and tumours harbouring BRAF or NRAS mutations." (PMID 35993275, 2022). "Next, we examined the data reported recently by the Molloy laboratory, that analyzed samples coming from patients with metastatic BRAF/NRAS melanoma." (PMID 36776379, 2022). "In NRAS mutant melanoma the combination of volasertib and a MEK inhibitor (JTP-74017) had antitumor effects both in vitro and in vivo." (PMID 35719948, 2022). "The described pattern of NF1 mutant melanoma having the largest number of mutations within the three main subtypes of BRAF, NRAS, or NF1-mutated melanomas was apparent in our ARID1A mutated cohort." (PMID 35565222, 2022). "To date, no NRAS-specific targeted therapy has been approved, though various inhibitors targeting the MAPK pathway and several combination therapies have been evaluated for NRAS-mutant melanoma." (PMID 35954441, 2022). "Actually, we also performed additional analysis of NOTCH4 predictive value within NRAS mutant melanoma both in the discovery and validation cohorts." (PMID 35967450, 2022). "NRAS mutant melanoma cells preferentially use CRAF instead of BRAF (the preferred isoform for signaling in normal melanocytes)." (PMID 36402789, 2022). "In human melanoma, DGAT1 amplification was observed to co-occur with BRAF and NRAS mutation but also independently of either." (PMID 35732120, 2022). "Mechanistically, human melanomas with BRAF and NRAS mutations facilitate MITF expression and upregulate the level of the transcriptional coactivator PGC1α." (PMID 36612059, 2022). "Our study demonstrates that in BRAF- and NRAS-mutant MITF-proficient melanoma, the DUSP4 MAPK phosphatase restricts MAPK activation and prevents oncogenic overdose through modulation of MITF function." (PMID 35580987, 2022). "NRAS, the first oncogene identified in melanoma, is the one predominantly mutated among the RAS isoforms in melanoma (15–30% of cases)." (PMID 36400750, 2022). "Of note, several CDKN2A patients have been reported with melanomas with coexisting BRAF and NRAS mutations, which is uncommon in sporadic melanomas." (PMID 35372037, 2022). "We used this suite of TN mice to determine if NRAS oncogenes common to human melanoma drive melanocyte transformation better than those present in other tumor types." (PMID 35672316, 2022). "There are a handful of early genetic events linked to the development of melanoma in situ, including mutations in BRAF, NRAS, or NF1." (PMID 36143375, 2022). "Elevated BRAF-BRAF and BRAF-CRAF dimers were consistently observed in MEFs and primary melanocytes expressing NRAS mutants with strong melanoma-driving potential." (PMID 35672316, 2022). "NRAS amplification is, however, more common in human melanomas with an NRAS codon 12 or 13 mutant, supporting our observations that endogenous NRAS codon 12 and 13 mutants are insufficient to drive melanomagenesis." (PMID 35672316, 2022). "Melanomas have high frequency of mutations that include mutant BRAF, mutant NRAS, mutant neurofibromatosis type 1 (NF1), and the triple wild type." (PMID 35055084, 2022).
melanoma (continued). "The siUHMK1 + Tram combination resulted in more robust growth inhibition in multiple NRAS mutant melanoma cell lines providing evidence that UHMK1 depletion can also play a role in MAPK targeted therapy response in the setting of a different oncogenic driver." (PMID 35232962, 2022). "Our combined results suggest that two pathways are activated in drug resistance of NRAS mutant melanoma and that CD133 contributes to at least one of these pathways via AKT and the BCL-2 family, while the other pathway involves MAPK." (PMID 35216449, 2022). "We detected mutations in six genes in the EVs (BRAF, NRAS, CDKN2A, STK19, PPP6C, and RAC), and at least one mutation was detected in all melanoma EV samples." (PMID 36531960, 2022). "Metabolic reprogramming in melanoma cells is strongly linked to the constitutive activation of MAPK and PI3K signaling induced by driver mutations such as BRAF and NRAS mutants, leading to various metabolic phenotypes." (PMID 35851093, 2022). "We employed CRISPR/Cas9 genome engineering to introduce NRAS Q61K, KRAS G13D and MEK1 Q56P mutations into the A375 melanoma cell line with endogenously high expression of BRAF V600E." (PMID 36358868, 2022). "There is also an overlap in genes associated with melanoma and the RASopathies, in that mutations in BRAF, NRAS, and NF1 in melanoma are also well‐known RASopathy‐associated genes." (PMID 35266292, 2022). "The melanoma cell line used in our experiments also carries a mutation upstream of ERK1/2, affecting HRAS and NRAS genes." (PMID 35563794, 2022). "Binimetinib represents a new treatment option for patients with NRAS-mutant melanoma after the failure of immunotherapy." (PMID 36551302, 2022). "Exploiting the expression of melanogenesis-associated transcription factor target gene CYP27A1 and inhibiting mitochondrial OxPhos suggest a strategy for BRAF/NRAS mutant melanoma." (PMID 35311151, 2022). "MEK inhibitor binimetinib was used in a phase III trial to assess the efficacy and safety against NRAS-mutant melanoma, however, data is as yet insufficient to reach a definite conclusion as to its efficacy improvement." (PMID 35534592, 2022). "In solid tumors, resistance to MEK inhibitors in human melanomas with BRAF and NRAS mutations is mediated by high OXPHOS activity, which is attenuated by mTORC1/2 inhibitors." (PMID 36612059, 2022). "They explored the relative frequency of genetic factors(BRAF/NRAS/p16CDKN2A) known to play an important role in melanoma development, and their distribution among different melanoma tissues and disease progression sites by sequencing DNA from tissue samples." (PMID 36091077, 2022). "Expression of PPP6C(R264C) cooperated with oncogenic NRAS(Q61K) to accelerate melanoma initiation in zebrafish, consistent with a gain of function alteration." (PMID 35368039, 2022). "Overall, we conclude that UBIAD1 and CoQ10 are significantly expressed during melanoma progression as well as in melanoma cells carrying both BRAF and NRAS mutations." (PMID 35255427, 2022). "Within this study, the effect of a so far well-characterized antitumor peptide, RDP22 (R-DIM-P-LF11-322) on the highly aggressive melanoma metastasis cell line MUG-Mel2, carrying an NRAS mutation, was investigated." (PMID 36428530, 2022). "For example, in NRAS-mutant melanoma, RAS mis-localized to the cytoplasm in response to shLZTR1 and caused MAPK inhibition." (PMID 35197475, 2022). "Based on BRAF, NRAS and TERT promoter mutations, the custom melanoma panel displayed a limit of detection of ~0.2% mutant allele frequency and showed significant correlation with droplet digital PCR." (PMID 35494035, 2022).
melanoma (continued). "MEK inhibitor monotherapy has activity in BRAF V600 wild-type, NRAS Q61R/K/L mutant melanoma and BRAF V600 wild-type/NRAS Q61R/K/L wild-type melanoma but is associated with considerable treatment-limiting skin toxicity." (PMID 36058945, 2022). "Recently, a zebrafish model has been generated to study NRAS mutant melanoma using the MiniCoopR vector (mcr:NRAS)." (PMID 35883768, 2022). "Most of the completed and ongoing clinical trials involving combination therapy for advanced NRAS-mutant melanoma target signaling molecules upstream or downstream of Ras, such as MEK and RAF." (PMID 35954441, 2022). "Fewer than 35 genes were differentially expressed between tumors carrying NRAS mutants considered to be strong melanoma drivers." (PMID 35672316, 2022). "To better characterize the role of ARAF in NRAS-driven melanoma, we searched for new ARAF interactors by mass spectrometry." (PMID 35091687, 2022). "One study reported a significantly higher response rate and clinical benefit for patients with NRAS-mutant melanoma compared to patients with NRAS-WT tumors receiving immunotherapy." (PMID 35234863, 2022). "Though NRAS and PTEN mutations are mutually exclusive in melanomas, an oncogenic RAS also can trigger the PI3K–AKT–mTOR pathway." (PMID 36135270, 2022). "The results of this study suggest a combination therapy with TAK1 inhibitor and trametinib as an effective therapeutic approach for the treatment of NRAS-mutant melanoma." (PMID 35715750, 2022). "For melanoma, BRAF and NRAS mutations are considered to be important disease-driving oncogenes and were included in the mutation analysis performed in this study." (PMID 36531960, 2022). "In melanoma, NRAS is one of the most significant driver genes and comprises 15%–20% of all melanomas." (PMID 35967450, 2022). "Zhang found that many of these tumors are associated with BAP1 mutations, compared with nodular melanoma or superficial spreading melanoma, which are associated with BRAF and NRAS mutations." (PMID 36289768, 2022). "Only Dabrafenib has been reported to have potent inhibitory effect against BRAF-mutant melanoma and NRAS-mutant melanoma cell lines." (PMID 35436996, 2022). "Trametinib (and other second and third generation MEKi’s including binimetinib, selumetinib, pimasertib, and cobimetinib) are FDA-approved and are currently being explored for NRAS mutant melanoma in combination with other targeted agents and immunotherapies." (PMID 35216449, 2022). "By investigating the role of ARAF in NRAS-driven mouse melanoma through mass spectrometry experiments followed by a functional siRNA-based screen, we unexpectedly identified MITF as a direct ARAF partner." (PMID 35091687, 2022). "Even though loss-of-heterozygosity is uncommon in NRAS-driven human malignancies, NRAS61R was unable to drive melanoma formation in the presence of wild-type NRAS61Q." (PMID 35672316, 2022). "Contemporary, it has been reported that mutation in both NRAS and BRAF is linked with poor prognosis in stage IV of melanoma cases." (PMID 36224606, 2022). "Several genes have been identified as genetically altered drivers of melanoma tumorigenesis, such as NRAS, CDNK2A, MITF, PTEN, KIT, GNAQ, GNA11 or CTNNB1, but most (60%) melanomas have BRAF gene mutations." (PMID 35326682, 2022). "Our previous study also showed that IFI6 is a target of NRAS and promotes tumor growth by suppressing DNA replication stress in melanoma cells." (PMID 36338541, 2022). "A study showed that co-inhibition of MEK and ERK5, a compensatory pathway activated by MEKi possibly via receptor tyrosine kinase PDGFRβ, suppressed growth and progression of NRAS-mutant melanoma cells in vitro and in xenografts." (PMID 35954441, 2022).
melanoma (continued). "About 50% of melanomas carry activating mutations in the BRAF oncogene and about 30% in the NRAS gene leading to overactivation of the mitogen-activated protein kinase (MAPK) pathway, making this signaling cascade a preferential target for melanoma treatment." (PMID 35884430, 2022). "It suggests that PDPK1 play a significant role in tumour-promoting performance in patients with NRAS mutant melanoma." (PMID 36551688, 2022). "Research has shown that TIL infiltration levels in NRAS wildtype melanoma are higher than in NRAS mutant melanoma." (PMID 35967450, 2022). "MEK162 is also evaluated in combination with third generation cyclin dependent kinases 4 and 6 (CDK4/6) inhibitor, Ribociclib (LEE001), showing increased antitumour activity and safety in advanced NRAS and BRAF mutated melanoma." (PMID 35993275, 2022). "Four BRAF-V600/NRAS mutant pre-treated patients with locally advanced or metastatic melanoma and one patient (#A30) with de novo metastases during adjuvant therapy for radically resected BRAF-V600/NRAS wild-type melanoma were tested." (PMID 35804825, 2022). "Trametinib is reported to induce apoptosis at varying levels and, overall, it is less potent/efficacious in NRAS mutant melanoma cell lines compared to BRAF mutant melanoma cell lines." (PMID 33921974, 2021). "BRAF-mutant melanomas are more likely than NRAS-mutant melanomas to arise in anatomical locations protected from chronic sun damage." (PMID 34210801, 2021). "BRAFV600E resistance develops during treatment and, similarly, resistance also appears when NRAS-mutant melanomas are treated with targeted drugs." (PMID 34063141, 2021). "Increased signaling activity of the mitogen‐activated protein kinase (MAPK) pathway is a hallmark of melanoma and can be attributed to mutations in the BRAF, NRAS, KIT, or NF1 genes." (PMID 32767816, 2021). "Pimasertib, a second-generation MEK1/2 inhibitor, also showed an improvement in the PFS over dacarbazine (13.0 vs. 6.9 weeks) in a phase 2 study in NRAS mutant melanomas; however, the OS was similar." (PMID 34831002, 2021). "A significant relationship was found between advanced melanoma stages and increased BRAF/NRAS mutation rate (p ≤ 0.001)." (PMID 33723350, 2021). "Stable expression of sh-ID3 in the NRAS-mutant melanoma M93–047 cell line also led to increased sensitivity to PD901 and to trametinib, another MEKi; this effect was recapitulated in pooled stably infected cell lines as well as two independent clones." (PMID 35187538, 2021). "In this study, we analyzed the prognostic role of NRAS, KIT, BRAF, IGF2R and SF3B1 mutations in a series of mucosal melanomas." (PMID 34571863, 2021). "In agreement, ERK5 knockdown in NRAS-mutant melanoma cells with increased basal ERK5 activity only transiently impaired the G1-S progression but did not affect long-term proliferation." (PMID 34299213, 2021). "The combination of CCG-222740 and trametinib induced apoptosis and inhibited clonogenicity in those NRAS mutant melanoma cell lines that have increased Rho/MRTF activation and are strongly resistant to trametinib." (PMID 33921974, 2021). "Compared to melanoma patients with BRAFV600 mutations, patients with activating NRAS mutations have more aggressive disease progression and poorer outcomes." (PMID 33921974, 2021). "In line with this, it is well-understood that SOX10 expression is required for melanoma formation in NRAS-mutant mouse melanomas." (PMID 34930891, 2021). "Accordingly it has been reported that ERK1 and ERK2 overexpression results in cell death in BRAF and NRAS‐mutant melanoma cells." (PMID 32767816, 2021).
melanoma (continued). "In a small series of 19 primary cutaneous head and neck melanomas, including five melanomas of the scalp, we recently found the majority of cases to be a wild type for BRAF and NRAS, with BRAF mutations observed in only 23% of the melanomas." (PMID 33525348, 2021). "To date, treatment options for NRAS mutant melanoma patients are limited to chemotherapeutics and immunotherapies, both of which are associated with high toxicity and/or low response rates." (PMID 33921974, 2021). "The Ras/MEK/ERK pathway has been the primary focus of targeted therapies in melanoma; it is aberrantly activated in almost 80% of human cutaneous melanomas (≈50% BRAFV600 mutations and ≈30% NRAS mutations)." (PMID 33921974, 2021). "In our study, the ORRs and DCRs of NRAS mutant melanoma patients were lower than those of wild-type patients, and NRAS mutation was associated with worse survival in the noncutaneous group with a significant difference." (PMID 34290710, 2021). "We show that HSP70 inhibitors synergize with MEKi against NRAS-mutant melanoma, and that this combination significantly enhances the survival of mice in two different models of NRAS-mutant melanoma." (PMID 35187538, 2021). "Upon Usp9x KD, colony growth in 3D culture was blocked in both BRAF (A375) and NRAS (WM1366)-mutant melanoma cells." (PMID 33613844, 2021). "Instead, the MAPK signaling is aberrant activated also by missense mutation charged to neuroblastoma RAS viral oncogene homolog (NRAS), a member of the RAS gene family, involved in the regulation of cell growth, and particularly important for melanoma onset." (PMID 33917181, 2021). "We first tested the human melanoma brain metastatic cell line WM4265.2, which is derived from a patient-derived xenograft tumor and has a mutation in NRAS." (PMID 35187538, 2021). "The effects and mechanisms of PPP2R3B overexpression were modeled in detail by creation of a stable inducible overexpression system in two NRAS-mutant melanoma cell lines SKMEL2 and SKMEL30." (PMID 34145395, 2021). "For example, inhibiting a novel NRAS-activating kinase (STK19) and combining MEK inhibitors with inhibitors of the MER receptor tyrosine kinase (MERTK), BET, and HDAC have been reported to block NRAS mutant melanoma growth in vitro and in vivo." (PMID 33921974, 2021). "Though there is disagreement on the specific correlations between melanoma metastasis and BRAF/NRAS mutation status, BRAF and NRAS mutations are known to be stage-independent risk factors for worse prognosis in the metastatic setting." (PMID 35008286, 2021). "Preclinical evidence suggests the antitumor synergistic efficacy of CDK4/6 inhibitors, with BRAF/MEK inhibitors and MEK inhibitors, in BRAF and NRAS mutant melanomas, respectively." (PMID 34831002, 2021). "Considering that several ETS factors are direct targets of MAPK pathway signaling, an examination of YK-4-279 treatment for both BRAF and NRAS driven melanomas has significance." (PMID 35008307, 2021). "Further clinical trials have investigated the therapeutic use of two additional MEK inhibitors under investigation for NRAS-mutant melanomas." (PMID 33807778, 2021). "Although the main events leading to melanoma progression and drug resistance are genetic events (mainly BRAF and NRAS mutations), epigenetic mechanisms are also important." (PMID 34063141, 2021). "Usp9x KD but not Usp34 KD reduced SOX2 levels in both BRAF mutant A375, SK-Mel28, and NRAS-mutant SK-Mel147 melanoma cell lines." (PMID 33613844, 2021). "We subcutaneously injected cells from the MaNRAS1014 or M93–047 NRAS-mutant melanoma cell lines into the flanks of NSG mice." (PMID 35187538, 2021). "The union of the melanoma core RS and con‐GCRs comprise 11 distinct rules and are dominated by rules that contain either BRAF or NRAS mutations." (PMID 33769711, 2021).